CNTN3 (contactin 3)
Description:
Contactins mediate cell surface interactions during nervous system development. Has some neurite outgrowth-promoting activity (By similarity).
Synonyms: BIG-1; PANG; PCS
Tractability: Antibody: its Gene Ontology location is reachable by antibodies, with high confidence; UniProt places it where antibodies can reach, with medium confidence; UniProt predicts a signal peptide or a membrane-spanning region. PROTAC: its protein half-life has been measured.
Gene: Protein-coding gene on chromosome 3 (74,262,568 to 74,614,698, reverse strand). Ensembl gene ENSG00000113805.
Subcellular location: Cell membrane
Pathways (Reactome):
Metabolism of proteins: Post-translational modification: synthesis of GPI-anchored proteins
Gene Ontology:
Cellular component: extracellular region; neuron projection; plasma membrane
Genetic constraint (gnomAD): Loss-of-function variants: 45 observed, 86.39 expected, observed/expected ratio (o/e) 0.52, 90% interval 0.41 to 0.67. The upper end of that interval is the gene's LOEUF score, 0.67, which puts it in group 2 of 6, group 1 being the genes least tolerant of losing a copy. Missense variants: 867 observed, 1,006.8 expected, observed/expected ratio (o/e) 0.86, 90% interval 0.81 to 0.91. Synonymous variants: 359 observed, 355.42 expected, observed/expected ratio (o/e) 1.01, 90% interval 0.93 to 1.1.
Homologues: Orthologues: macaque CNTN3 (98% identical), chimpanzee CNTN3 (98% identical), rabbit CNTN3 (93% identical), guinea pig CNTN3 (93% identical), pig CNTN3 (92% identical), mouse Cntn3 (91% identical), rat Cntn3 (88% identical). Paralogues in human: CNTN4 (64% identical), CNTN6 (59% identical), CNTN5 (55% identical), CNTN2 (44% identical), CNTN1 (43% identical), NRCAM (29% identical), L1CAM (29% identical), CHL1 (28% identical), NFASC (26% identical), NEO1 (24% identical), DCC (23% identical), ROBO1 (23% identical), and 24 more.
Diseases named in the same sentence as CNTN3 in open-access papers:
CNTN3 is named in the same sentence as 28 diseases in open-access papers, as found by Europe PMC text mining. Sharing a sentence is not in itself a finding about the gene and the disease. The quoted sentences say what the papers report.
glioblastoma (3 papers, 2020 to 2025). The most malignant astrocytic tumor (WHO grade IV). "High expresssion of CD44 and lower expression level of CNTN3 were both related to the poor prognosis of glioblastomas." (PMID 32775408, 2020). "Another study shows that the lower expression levels of CNTN3 may be an independent biomarker that predicts poor overall survival time in patients with glioblastoma multiforme." (PMID 32566650, 2020).
abdominal aortic aneurysm (1 paper, 2019). Enlargement and ballooning of the vessel that supplies arterial blood to the abdomen, pelvis and legs. "Genetic variants of human CNTN3 are associated with an autism spectrum disorder and vascular abnormalities underlying abdominal aortic aneurysms." (PMID 31645420, 2019).
anaphylaxis (1 paper, 2019). An acute hypersensitivity reaction that occurs from exposure to an allergen. "This approach identified several genes that are associated with aging (ATP2B2, CAV3, CNTN3, CTNNA2, GRID2), inflammation (ATP2B2, CAV3, RAD18, KBTBD8), vascular permeability (SFXN5, RAD18) and anaphylaxis (CAV3, RAD18, CTNNA2, ATP2B2 and GRID2)." (PMID 31701027, 2019).
autism (1 paper, 2013). Persistent deficits in social interaction and communication and interaction as well as a markedly restricted repertoire of activity and interest as well as repetitive patterns of behavior. "Some of the genes, such as NCAN and EPHA7, have similar functionality as NRXN1 in mediating neuronal cell interactions, while some other genes, such as PCDH19, CNTN3, CTNNA3, LMX1B, are known autism candidate genes." (PMID 23536886, 2013).
breast carcinoma (1 paper, 2020). "For cancer, a previous study suggested that CNTN3 is a potential target gene of hsa-miR-3675b in breast cancer, and it was demonstrated that CNTN3 may be associated with cell proliferation, apoptosis, and cell cycle progression." (PMID 32566650, 2020).
cerebellar pilocytic astrocytoma (1 paper, 2015). A WHO Grade 1 astrocytoma which arises in the cerebellum. "This is the first report where CNTN1 and CNTN3 gene expression were shown to be connected with cerebellar pilocytic astrocytomas biology." (PMID 26497896, 2015).
cerebellar tumors (1 paper, 2015). "Contactin family genes (CNTN1, CNTN3), which function as cell adhesion molecules with an essential role in later stages of cerebellar morphogenesis and differentiation, were also significantly overrepresentated in our cohort of cerebellar tumors." (PMID 26497896, 2015).
colon adenocarcinoma (1 paper, 2020). "In colon adenocarcinoma and rectum adenocarcinoma, the expressions of CEACAM7 and CNTN3 were significantly positively correlated with infiltrating levels of B cells." (PMID 32566650, 2020).
colorectal cancer (1 paper, 2020). A primary or metastatic malignant neoplasm that affects the colon or rectum. "Three novel genes, CNTN3, SLC1A1, and SLC16A9 were shown to have diagnostic value with respect to the occurrence of colorectal cancer and should be verified in future studies." (PMID 32566650, 2020).
hepatocellular carcinoma (1 paper, 2025). A malignant tumor that arises from hepatocytes. "In conclusion, this study identified and internally evaluated a five-gene metabolic signature (PLPPR1, CNTN3, HOXA10, HAGLR, and ENPP3) associated with immunotherapy response in hepatocellular carcinoma through integrative analysis of multiple transcriptomic datasets." (PMID 41515582, 2025).
neuroblastoma (1 paper, 2022). Neuroblastoma (NB) is the most common solid, extracranial childhood tumor. "CNTN3 expression was induced in the differentiated SH-SY5Y neuroblastoma cells in vitro (fold change = 6.2, p < 0.01)." (PMID 35030990, 2022). "The expression of contactin-3 was further analyzed in fetal and postnatal control tissue by western blotting and in-situ hybridization, as well as in the SH-SY5Y neuroblastoma cell line differentiation model in vitro." (PMID 35030990, 2022).
salpingitis (1 paper, 2023). Acute or chronic inflammation of the fallopian tube. "In this study, HK2 and MOGAT1 were upregulated and CA4, CNTN3, and ACAN were downregulated in the CN-LPS group, suggesting that LPS-induced salpingitis caused abnormal lipid and sugar metabolism and altered the acid–base balance of the internal environment, degrading the extracellular matrix." (PMID 37978561, 2023).
Systemic capillary leak syndrome (1 paper, 2019). Systemic capillary leak syndrome (SCLS) is a severe systemic disease due to increased capillary permeability, characterized by episodes of hypotension, edema and hypovolemia. "Intriguingly, CNTN3 is near a segregating SNP for Systemic Capillary Leak Syndrome (SCLS) from a human GWAS." (PMID 31645420, 2019).
cancer (3 papers, 2020 to 2023). A tumor composed of atypical neoplastic, often pleomorphic cells that invade other tissues. "Aberrant expression of ARHGAP12, ATG5 and CNTN3 is associated with different types of carcinomas." (PMID 37026480, 2023).
tumor (3 papers, 2020 to 2023). "Seven genes (CACNB2, IL34, CGNL1, CNTN3, GAS7, HOPX, and PBX1) regulated by miR-31-5p and miR-31-3p were identified as putative tumor suppressors." (PMID 34201353, 2021). "With down-regulation of CNTN3, EGFR may be abnormally activated and initiate ErbB signaling to promote tumor growth and invasion." (PMID 37978561, 2023).
intestinal diseases (1 paper, 2020). "At present, there is still a lack of research into SLC1A1, SLC16A9, and CNTN3 related to intestinal diseases." (PMID 32566650, 2020).
neurodevelopmental disorder (1 paper, 2022). A behavioral and cognitive disorder with onset during the developmental period that involves impaired or aberrant development of intellectual, motor, or social functions. "Further analysis is warranted for contactin-3 and the associated network of proteins in TSC as well as other neurodevelopmental disorders." (PMID 35030990, 2022).
CNTN3 also shares sentences with these, for which no sentence is quoted: plasmacytoma (5 papers); autism spectrum disorder (1); colorectal adenoma (1); epilepsy (1); Focal cortical dysplasia (1); Intellectual disability (1); microcephaly (1); Neurodevelopmental delay (1); rectum adenocarcinoma (1); tuberous sclerosis complex (1); ulcerative colitis (1).